IL4 (interleukin 4)
Diseases named in the same sentence as IL4 in open-access papers (continued):
Sharing a sentence is not in itself a finding about the gene and the disease.
infection (continued). "To investigate whether a similar immune response characterized by diminished induction of Th2 cytokines could also be found at the infection site, we measured the percentages of CD4+IFN-γ+, CD4+IL-10+, and CD4+IL-4+ T cells in the challenged ears of control and vaccinated mice at 10 wpc." (PMID 35236861, 2022). "Generally, in the acute phase of infection, proinflammatory cytokines that include IFN-γ, tumor necrosis factor-alpha (TNF-α), IL-1β, and IL-12 are related to parasite control, and anti-inflammatory cytokines (IL-10, IL-4, and transforming growth factor-beta [TGF-β]) result in opposing actions." (PMID 36389843, 2022). "However, the intensity of the IL-4+ mCD4+ T cell response at 7–12 months post vaccination in the hybrid-immunity group was not different from that in the infection-only group, while it was lower than that at 1–6 months post vaccination." (PMID 36494338, 2022). "Furthermore, the unique pattern of IL-8, IL-13 and MCP-3, but not IL-4 expression was also recapitulated using experimental in vitro infection in PBMCs." (PMID 34215212, 2021). "B cells activated with CD40L and interleukin-4 (IL-4), which mimics signals received from activated CD4+ T cells, express the C-type lectin DC-specific intercellular adhesion molecule-3-grabbing nonintegrin (DC-SIGN) and can capture HIV-1, leading to trans infection of CD4+ T cells." (PMID 33688006, 2021). "Interestingly, cytokines like IL-4 (DF vs DSS, p<0.01), IL-8 (DF vs DHF, p<0.05 and DF vs DSS, p<0.05), and IL-10 (DF vs DHF, p<0.0001 and DF vs DSS, p<0.01) had significant upregulation in acute phase of infection (DF) than the DHF and DSS." (PMID 34447698, 2021). "Moreover, IL-4 stimulation down-regulated TGF-β1 and IFN-γR1 expression on naïve T cells, possibly signifying the broad regulatory implications of IL-4 in conditioning lineage commitment decisions during early infection." (PMID 34006897, 2021). "The mRNA level of IL-4 was absent while IL-10 occurred during the later phase of infection." (PMID 33680991, 2021). "The previous data, showing that the transfer of BALB/c highly expressing IL-4 cells to genetically resistant chimeric mice on a C57BL/6 background did not result in susceptibility, suggested that the infection outcome is not governed only by the type of cytokine produced." (PMID 34036108, 2021). "Further, IL-4 production in resistant mice does not alter the evolution towards progressive disease, similarly seen in C3H mice treated with IL-4 or anti-IL-12 at the beginning of infection." (PMID 34036108, 2021). "Furthermore, only STAT1+/+ mice developed M2 macrophages at 8 weeks post-infection, although macrophages from both T. crassiceps-infected STAT1+/+ and STAT1−/− mice responded to IL-4 in vitro, and both groups of mice were able to produce the Th2 cytokine IL-13." (PMID 34684235, 2021). "Moreover, the rate of infection was unable to induce the IL-4 response without proper expression of IL-4 mRNA or protein level." (PMID 34226412, 2021). "On day four post-infection, the levels of pro-inflammatory cytokines TNF-α and IFN-γ were decreased to 6.6 and 2.5 times that observed in controls respectively while the levels of anti-inflammatory cytokine IL-10 and IL-4 were increased (by 2.1 and 5.7 times) upon quercetin treatment." (PMID 33803419, 2021). "Importantly, in the absence of IL-13 expression, neither IL-4 nor IL-5 cytokine expression was changed in CD4+ T cells after infection." (PMID 34127548, 2021). "IL-4 levels remained undetectable throughout infection (data not shown)." (PMID 34248935, 2021). "The results of cytokine secretion showed that although the percentages of IL-4-, IL-10-, and IL-12-secreting DCs from WT mice increased significantly after infection (P < 0.05), no marked difference was found between infected WT and infected TLR7 KO mice (P > 0.05)." (PMID 34692568, 2021).
infection (continued). "Moreover, on day 72 p.i., IL-4 and IL-5 were the only cytokines which were increased in the TC of recipient mice following a transfer of CD4+ T cells, whereas the majority of the cytokines and chemokines were actually reduced at the site of infection." (PMID 34868049, 2021). "Moreover, IL-4Rα -deficient and IL-4Rα sufficient BMDCs produced similar levels of IL-12p70 and IL-10 during infection hence suggesting that IL-4-mediated DC instruction was not impaired in CD11ccreIL-4Rα-/lox." (PMID 35154068, 2021). "Importantly, the IL-4 environment can also significantly impact the quality/avidity of T cell immunity, where IL-4R⍺ expression was inversely related to IFN-γ and TNF expression on effector T cells following infection/vaccination." (PMID 34006897, 2021). "There was no expression of IL4 observed post one hour of infection." (PMID 35011356, 2021). "By analysing cytokines associated with the major CD4+ve Thelper (Th) cell subsets (Interferon-gamma (IFN-γ)/Th1; Interleukin (IL)-4/Th2; IL-17A/Th17; IL-10/Tregulatory), we show that there is selective activation of PBMC producing IFN-γ and/or IL-10 during the latent phase following infection." (PMID 32487248, 2020). "No significant secretion of IL-4 and IL-10 was observed in any experimental group before infection." (PMID 32526867, 2020). "Among the 16 hypothesis-driven models tested, the option that best captures the dynamics of infection for both helminths is M12, which includes IgA stimulation by IL4 and by the parasite, P, and excludes the other mechanisms." (PMID 33226981, 2020). "A direct requirement for IL-4/IL-13 signaling in worm expulsion is demonstrated by IL-4 receptor antibody blocking experiments, and in IL-4R−/− and STAT6−/− mice, dramatically limiting worm expulsion during T. muris, Heligmosomoides polygyrus or N. brasiliensis infection." (PMID 33193437, 2020). "Levels of interferon-gamma (IFNγ) production were high in mice treated with morphine before infection (just like the sulfadiazine plus pyrimethamine) compared with those in the no drug group, whereas levels of interleukin 4 (IL-4) productions were low across all treatment groups." (PMID 32398975, 2020). "In contrast, infection of C57BL/6 mice with L. major induces a small lesion that is self-healing, a process linked with the differentiation of IFN-γ secreting Th1 cells and the absence of CD4+IL-4+ T cells." (PMID 33212818, 2020). "Although this study demonstrated B cells as a potential early source ofIL-4, these cells might not be the primary source of IL-4 following infection." (PMID 32948646, 2020). "Further IL-4/IL-13 stimulation does not upregulate SIGNR3 expression or enhance infection." (PMID 31825972, 2019). "Our previous study described that co-infected Ss infection with active or latent TB has significantly reduced Type 1 (IFN-γ, TNF-α, and IL-2), Type 17 (IL-17A and IL-17F) and increased regulatory as well as Type 2 (IL-4, IL-5, and IL-13) cytokines when compared to TB infection alone." (PMID 30897083, 2019). "Infection with murine cytomegalovirus induces CD1d‐independent IFN‐γ (but not IL‐4) secretion by iNKT cells in the absence of expansion 46, suggesting that in vivo activation of iNKT cells in the absence of TCR signaling may not lead to proliferation." (PMID 30427069, 2019). "The stronger type 2 (IL4 and IL5) response and reduced abundance in the dual infection can be considered analogous to increased population mortality due to predation, which in turn could have led to the higher reproductive allocation and more eggs found in utero." (PMID 31871660, 2019). "We found that infection with the Mycobacterium tuberculosis Beijing-1585 strain or EAI-1627 strain is characterized by an influx of B-cells in the lungs and higher pulmonary IL-4 protein levels compared to a T cell-dominated response to the less virulent H37Rv strain." (PMID 31882653, 2019).
infection (continued). "Consequently, in this study we generated CD4+ T cell-specific IL-4Rα−/− (LckcreIL-4Rα−/lox) mice and iLckcreIL-4Rα−/lox mice that lack IL-4Rα on both CD4 and CD8 T cells to determine the temporal role of IL-4 signaling via CD4+ and CD8+ T cells on the progression of VL infection." (PMID 31475014, 2019). "However, we were able to demonstrate reduced secretion of Th2 cytokine IL4 by popliteal lymph node cells restimulated with soluble Leishmania antigen (SLA), both early after parasite inoculation (11d) and in established infection (4w)." (PMID 31749794, 2019). "Il4 increases the expression of non-canonical Wnt proteins during infection or inflammation." (PMID 30709343, 2019). "Thus, we speculate that, in the setting of infection or other IPP-inducing cellular stresses such as cancer, CL-induced activation of IL-4-producing γδ T cells in SSc, together with a decrease of IFNγ-producing γδ T cells, may contribute to organ fibrosis." (PMID 29706966, 2018). "However, it was shown from their data that IL4 was not expressed after infection and TLR4 decreased after infection." (PMID 29433383, 2018). "Importantly, when we injected anti-IL-4 3 days prior to infection, this reduction was not significant, suggesting that the blocking effect of this antibody only lasts for a few days." (PMID 29249358, 2018). "Infection with N. americanus may not affect the levels of IL-4 and arginase-1 (Arg-1) expression by the M2 macrophages, although it results inhigher numbers of CD206+CD23+IL-10+ monocytes." (PMID 30274434, 2018). "Twenty-four hours after infection, we assessed inflammatory responses of the macrophages by measuring the levels of cytokines, including granulocyte/macrophage colony-stimulating factor (GM-CSF), IFN-γ, interleukin (IL)-2, IL-4, IL-6, IL-8, IL-10 and TNF-α, secreted in the culture supernatant." (PMID 29712918, 2018). "As previously reported, in the clinical infection, the bovine MAP infection disease was characterized by a gradual shift in the immune responses from cell-mediated immune response to antibody mediated immune response while IL4, IL5 and IL13 can promote the Th2 antibody-mediated immune response." (PMID 30591025, 2018). "T-bet/IFN-γ co-expressing cells were detected in similar proportions within IL-4 and IL-13 producers from spleens of mice infected for 10 days and the frequencies of IFN-γ+ Th2/1 hybrids in Th2 cytokine producing populations were similar when comparing day 10 and 20 post infection." (PMID 28676845, 2017). "Finally, we demonstrate that, in contrast to IL-4 DCs, IFN-α DCs are impaired in their capacity to transfer HTLV-1 to CD4 T-cells, both after viral capture and trans-infection and after their productive infection." (PMID 28426803, 2017). "Furthermore, the absence of IL-4 secretion observed during our study renders it difficult to attribute infection development to a typical activation of Th2 cells." (PMID 28542438, 2017). "Notably, the presence of IL-4 induces up-regulation of MR expression on dermal macrophages and recruits monocyte-derived macrophages (MDM), thereby boosting further infection and pro-inflammatory events that may lead to disease progression." (PMID 29020083, 2017). "Only IL-4 had a similar expression between negative and positive congenial infections." (PMID 28458694, 2017). "However, this treatment did not promote resolution of the infection, which did not evidence a relation of IL-4 with the pathogenesis of the disease in this model." (PMID 28848541, 2017). "However, infection with L. infantum resulted in an increased expression of FoxP3, CD4+, TGF-β, IL-10, TNF-α and IFN-γ in the colon and jejunum and a reduction of CD8+ and IL-4." (PMID 27094260, 2017). "The results indicate that the expression levels of IFN-γ and IL-2, but not IL-6 and IL-4, were elevated in the Tris-HCl control or adjuvant vaccinated mouse splenocytes and had the potential for proliferation after infection of Babesia parasites or BMSA stimulation." (PMID 29312230, 2017).
infection (continued). "The early IL-4 response to L. major is confined to CD4+ T cells expressing a Vβ4+Vα8+ T cell receptor that recognizes the Leishmania antigen LACK (Leishmania homolog of receptors for activated C kinase), in addition to mast cells and eosinophils at the site of infection and draining LN." (PMID 29176972, 2017). "The lack of impact of IL-4Rα signaling on lesion development, parasite control, and the differentiation of CD4+ Th1 cells at the site of infection and in the dLN firmly demonstrated that IL-4 signaling on keratinocytes was not involved in Th1 cell differentiation following L. major infection." (PMID 29067025, 2017). "In addition to classical Th9 cells responding to antigen-stimulation, we also observed increased frequencies of Th2 cells expressing IL-9 (IL-4/IL-9 co-expressing), indicating that other CD4+ T cell subsets also respond to Ss infection with the capacity to produce more IL-9." (PMID 26730582, 2016). "Levels of IL-2, IL-4, IL-5 and IL-13 were unaltered by infection in the presence or absence of Mtb." (PMID 26894562, 2016). "Whilst T helper cells could obviously not be measured in antibody treated mice, an absence of induction of Il4, Il13 and Il17a mRNAs in the lung following infection supported an absence of Th2 and Th17 responses in CD4+ cell depleted mice." (PMID 27683080, 2016). "Infection with C. burnetii did not induce significant production of Il4 or Il10." (PMID 26366725, 2015). "Recovery from infection did not affect the other cytokines, including IL-10, IL-4 and IL-12." (PMID 26637129, 2015). "Similarly, infections in the presence of GM-CSF and IL-4 to support dendritic cell differentiation and maintenance also resulted in low or no infection." (PMID 26055104, 2015). "While the cellular levels of these factors vary between genetically divergent individuals and are known to contribute to the differential response to infection, the genetic loci that predispose macrophages to either the M(IFNG) or M(IL-4) phenotypes are not known." (PMID 26510153, 2015). "Interestingly, stimulation with TsCE, but not rTsCRT, resulted in increased synthesis of both IL-4 and IL-5 mRNA upon infection." (PMID 25811778, 2015). "However, by weeks 4 and 8 after infection, MGL1−/− mice produced significantly more IL-4 than the MGL1+/+ splenocytes in response to anti-CD3, whereas antigen-specific higher IL-4 production in MGL1−/− splenocytes was only observed at week 4 after infection compared with MGL1+/+ cells." (PMID 25664320, 2015). "However, unlike mangiferin, dexamethasone suppressed Th2 (IL-4, IL-5 and IL-13) responses as well as Th1 (IFN-γ and IL-12) responses, which is likely to increase patients' susceptibility on infection." (PMID 24955743, 2014). "Furthermore, peptidase-specific cytokine secretion, particularly the Th2 cytokines IL-4, IL-5, IL-13, was also observed in the immunized mice at 6 days after infection but not in the non-immunized mice." (PMID 24465551, 2014). "IL-4 was not expressed in the spleen at any time point during the infection period." (PMID 26664914, 2014). "While IFN-γ-producing Th1 cells do play a role in controlling acute infections, and they contribute to acute erythrocytic-stage pathology, it became apparent that a classical Th2 response producing IL-4 is not a critical feature of the CD4+ T-cell response during the chronic phase of infection." (PMID 25628621, 2014). "Similarly, although protective immunity to filarial infections in mice is dependent primarily on IL-4, IL-5 does not appear to play a role in resistance to infection." (PMID 24498448, 2014). "Accordingly, innate cytokines were found to be dispensable for IL-4 production after infection with several – but not all – helminths, suggesting that parasite products may be able to bypass the requirement for innate cytokines." (PMID 25360134, 2014). "However, expression of the trout IL-4/13 cytokine family member, IL-4/13A, was not affected by infection." (PMID 23865616, 2013).
infection (continued). "Consequently C57BL/6 mice infected with L. mexicana CPB null mutants, unlike infection with wild-type parasites, develop a healing response with reduced IL-4 production and TH2 responses along with elevated TH1 responses." (PMID 23437409, 2013). "The amounts of IL-4 or TGF-β detected in the serum on day 8 p.i. were not altered by infection." (PMID 24086456, 2013). "In addition, the level of IL-4 increased in serum from mice infected with S. rotundus at 15 days post-infection while no significant changes were detected in IL-17 level during infection regardless of Segniliparus spp." (PMID 23555735, 2013). "bakeri infection occurs independent of IL-4/-13-induced changes in the gut." (PMID 24040152, 2013). "The major breakthroughs in our understanding of HIV-1 cis and trans infection stem from discovery of simple methods for deriving large numbers of myeloid DC from CD34+ bone marrow stem cells using various growth factors and more importantly from blood monocytes using IL-4 and GM-CSF." (PMID 24278768, 2013). "Importantly, at the infection site, in the absence of Tfh cells, we found that ICOS deficiency actually led to an increased percentage of CD4+ T cells producing IL-4 and IL-13 protein." (PMID 23319295, 2013). "Additionally, no statistical difference was observed in TNF, IL-10 and IL-4 production in the organ under infection and STAg-pretreatment, despite TNF detection presented a trend to be lower in STAg-pretreated compared to PBS-pretreated mice." (PMID 24086456, 2013). "Thus, in contrast to IL-4-secreting CXCR5+ Tfh cells, not only are Th2 effector cell responses efficiently generated in ICOS−/− mice, it appears that ICOS is in fact involved in suppressing Th2 cell effector responses at the infection site." (PMID 23319295, 2013). "Protection against secondary infection depended on IL-4Rα and IL-13; but not IL-4." (PMID 24204255, 2013). "It has been demonstrated previously that during L. major infections high local Arginase-1 levels at the site of infection mediate L-arginine depletion, which results in impaired local CD4+ (and CD8+) T cell function, particularly IFN-γ production but also to a lesser extent IL-4 and IL-10." (PMID 23437409, 2013). "Expression levels of interleukin (IL)-4, IL-10, IL-13 and tumor necrosis factor (TNF)-α were significantly up-regulated while interferon (IFN)-α, IFN-β, IFN-γ, IL-1β,IL-2, IL-3, IL-15, IL-17F, IL-18 and colony-stimulating factor (CSF)-1 were markedly decreased in PBMCs at all stages of infection." (PMID 24358317, 2013). "Similarly, plasma samples of 22 out of 25 infected pigs at day 2 post-infection had increased secretion of IL-4, but none of the contact pigs produced detectable levels of IL-4." (PMID 22340040, 2012). "Analysis of cytokine responses in the CSF of mice detected IL-4 and IL-5 by two to three weeks post-infection, which were expressed by T-cells but not eosinophils; while eotaxin and macrophage inflammatory protein-1 in murine CSF were chemotactic for eosinophils in vitro." (PMID 22360486, 2012). "However, basophils may play a major role in type-2-mediated secondary infection in conjunction with CD4+ T cells, as depletion of IL-4 and IL-13 in both basophils and CD4+ T cells was necessary to abrogate protection." (PMID 22360486, 2012). "Levels of IL-4, IL-10 and IFN-γ from splenocytes were elevated in all infected animals compared to uninfected MBP-vaccinated animals when restimulated ex vivo with SEA and SWAP, indicating that infection-related cytokine responses were produced, although responses to SEA were generally higher." (PMID 22428079, 2012). "Localized gene expression for IL-4 was not significantly increased in the proximal colon at 53 days after inoculation, but was increased earlier in the course of infection which could have facilitated Campylobacter invasion in situ." (PMID 22532855, 2012).